REEP2 (receptor accessory protein 2)
Description:
Required for endoplasmic reticulum (ER) network formation, shaping and remodeling. May enhance the cell surface expression of odorant receptors (By similarity).
Synonyms: C5orf19; SGC32445; SPG72; Yip2d; SPG72A; SPG72B
Tractability: Antibody: UniProt predicts a signal peptide or a membrane-spanning region; its Gene Ontology location is reachable by antibodies, with medium confidence. PROTAC: ubiquitination databases record sites on it; its protein half-life has been measured.
Gene: Protein-coding gene on chromosome 5 (138,438,988 to 138,446,969, forward strand). Ensembl gene ENSG00000132563.
Subcellular location: Membrane
Subcellular location (Human Protein Atlas): Endoplasmic reticulum
Gene Ontology:
Molecular function: protein binding; microtubule binding; taste receptor binding
Biological process: endoplasmic reticulum tubular network organization
Cellular component: cytoplasmic microtubule; endoplasmic reticulum; endoplasmic reticulum membrane; endoplasmic reticulum tubular network; membrane; plasma membrane
Genetic constraint (gnomAD): Loss-of-function variants: 9 observed, 32.16 expected, observed/expected ratio (o/e) 0.28, 90% interval 0.17 to 0.49. The upper end of that interval is the gene's LOEUF score, 0.49, which puts it in group 2 of 6, group 1 being the genes least tolerant of losing a copy. Missense variants: 236 observed, 346.11 expected, observed/expected ratio (o/e) 0.68, 90% interval 0.61 to 0.76. Synonymous variants: 128 observed, 142.73 expected, observed/expected ratio (o/e) 0.9, 90% interval 0.78 to 1.04.
Homologues: Orthologues: macaque REEP2 (95% identical), guinea pig REEP2 (95% identical), pig REEP2 (95% identical), dog REEP2 (94% identical), rabbit REEP2 (93% identical), mouse Reep2 (93% identical), rat Reep2 (90% identical), chimpanzee REEP2 (84% identical), tropical clawed frog reep2 (74% identical), zebrafish reep2 (70% identical), Caenorhabditis elegans T19C3.4 (39% identical), Drosophila melanogaster CG5539 (24% identical), and 5 more. Paralogues in human: REEP1 (59% identical), REEP4 (54% identical), REEP3 (50% identical), REEP6 (19% identical), REEP5 (19% identical).
Diseases named in the same sentence as REEP2 in open-access papers:
REEP2 is named in the same sentence as 23 diseases in open-access papers, as found by Europe PMC text mining. Sharing a sentence is not in itself a finding about the gene and the disease. The quoted sentences say what the papers report.
hereditary spastic paraplegia (3 papers, 2015 to 2024). Hereditary spastic paraplegias (HSP) comprise a genetically and clinically heterogeneous group of neurodegenerative disorders characterized by progressive spasticity and hyperreflexia of the lower limbs. "Mutations in REEP1 and REEP2 cause Hereditary Spastic Paraplegia, but the function of these four REEP proteins remains enigmatic." (PMID 39368994, 2024). "REEP1 and REEP2 are enriched in neurons, and mutations in these proteins are linked to hereditary spastic paraplegia (HSP) and distal hereditary motor neuropathy type Vb (HMN5B), two related, inherited neuropathies caused by axonal shortening of motor neurons." (PMID 39368994, 2024).
Spastic paraplegia (3 papers, 2018 to 2024). Complete loss of the ability to move the lower limbs accompanied by spasticity of the lower limbs. "The REEP4 paralogs, REEP1 and REEP2, are associated with spastic paraplegia." (PMID 39262575, 2024). "Spastic paraplegia (SPG) has been linked to mutations in other family members (REEP1/SPG31 and REEP2/SPG72)." (PMID 39262575, 2024). "Mutations in REEP1 (OMIM 609139) and REEP2 (OMIM 609347) are associated with spastic paraplegia (SPG) types 31 (SPG31), and 72 (SPG72)." (PMID 29770609, 2018).
asthma (1 paper, 2024). "REEP2 was enriched in 12 items, with TOP 10 pathway as Graft Versus Host Disease, Allograft Rejection, Type I Diabetes Mellitus, Primary Immunodeficiency, Asthma, Basal Cell Carcinoma, Spliceosome, ECM Receptor Interaction, Wnt Signaling Pathway, Focal Adhesion." (PMID 38532632, 2024).
gastric cancer (1 paper, 2023). A primary or metastatic malignant neoplasm involving the stomach. "Moreover, REEP2 is a chemosensitivity-related gene in gastric cancer cells." (PMID 37238941, 2023).
tumor (1 paper, 2024). "Compared to non-tumor samples, REEP2, TMSB15A, DSEL, and ID4 were upregulated in NPC samples." (PMID 38532632, 2024). "DSEL, ID4, REEP2, and TMSB15A were upregulated in the NPC samples compared with the non-tumor samples." (PMID 38532632, 2024). "However, the expression of DSEL, ID4, REEP2, and TMSB15A not related the tumor progression." (PMID 38532632, 2024).
REEP2 also shares sentences with these, for which no sentence is quoted: amyotrophic lateral sclerosis (2 papers); acute myeloid leukaemia (1); autosomal dominant spastic paraplegia (1); autosomal dominant spastic paraplegia 31 (1); autosomal dominant spastic paraplegia 3A (1); autosomal dominant spastic paraplegia 4 (1); basal cell carcinoma (1); diabetes mellitus (1); distal hereditary motor neuropathy (1); Dystonia (1); major depression disorder (1); memory impairment (1); myelodysplastic syndrome (1); Primary Immunodeficiency (1); retinitis pigmentosa (1); spinocerebellar ataxias (1); Troyer syndrome (1); type 1 diabetes mellitus (1).